ADAM17 (ADAM metallopeptidase domain 17)
Diseases named in the same sentence as ADAM17 in open-access papers (continued):
Sharing a sentence is not in itself a finding about the gene and the disease.
cancer (continued). "ADAM17 acts as a molecular switch, regulating inflammation and tissue regeneration, thereby participating in the inflammation–cancer transition." (PMID 40143211, 2025). "ADAM17 is upregulated following the knockdown of miR-338-3p, which promotes cancer cell proliferation and metastasis." (PMID 39972489, 2025). "A mounting body of evidence has emerged linking ADAM17 to the pathogenesis of various diseases, including inflammation, cancer, cardiovascular and neurodegenerative diseases, highlighting its potential as a therapeutic target." (PMID 41050403, 2025). "Zhao and Hu (2013) demonstrated that gallic acid decreases HeLa and HTB-35 cancer cell viability, possibly through suppression of ADAM17 and downregulation of various signaling pathways." (PMID 41241661, 2025). "Additional, recombinant expression of the ADAM17 disintegrin-like domain impairs fibroblast-cancer cell interaction." (PMID 40224489, 2025). "C12 mAb, which targets the cysteine-rich domain of ADAM17, demonstrates a moderate anti-proliferative effect across a range of cancer cell lines." (PMID 41050403, 2025). "Membrane EpCAM is cleaved by ADAM17/TACE in the extracellular space; however, high expression of ADAM17/TACE is observed only in some cancer cells." (PMID 38791091, 2024). "The canonical pathways show that ADAM17 activation is accompanied with cancer, cellular stress and injury, extracellular matrix organization, metabolism of proteins and other signaling pathways." (PMID 38341954, 2024). "In contrast, ADAM17 has already been identified as a major mediator of therapy resistance and prognosis in cancer." (PMID 39286024, 2024). "The utilization of an anti-ADAM17 antibody or small molecule inhibitor can be considered for inhibition of CD16 shedding in case of combined cancer immunotherapy with antibodies, needing NK cells capable of mediating ADCC." (PMID 38994999, 2024). "Further findings revealed a significant correlation between elevated levels of ADAM17 and poor outcome in BC patients and consequently provided further motivations for applying ADAM17 as a cancer treatment target." (PMID 38317965, 2024). "iRhoms are highly specific ADAM17 regulatory cofactors with corresponding functions in inflammation, immune and growth factor signaling, and cancer." (PMID 38781971, 2024). "Our findings provide new insights into understanding of post-translational regulation in CD8+ T cell differentiation and functionality, and highlight ADAM17 as a potential therapeutic target for the development of cancer immunotherapies." (PMID 38918390, 2024). "Release of these substrates is crucially involved in various (patho-)physiological processes highlighting the central role of ADAM17 in development and in the immune response but also in chronic inflammation and cancer." (PMID 38409522, 2024). "Both iRhom1 and iRhom2 have long been known to regulate EGFR activity, a critical oncogenic signaling in multiple types of cancer, through regulating ADAM17 activity." (PMID 38177179, 2024). "It has been shown that cellular integrin α5β1 and exosomal ADAM17 mediate the binding and uptake of these exosomes in cancer cells." (PMID 39703513, 2024). "Modification on activating receptors such as CD16 is needed to avoid CD16 from being cleaved by metalloproteinase, ADAM17 which is released by cancer cells." (PMID 38726000, 2024). "The expression of ADAM17 was first explored in pan-cancer using The Cancer Genome Atlas (TCGA) cohort." (PMID 38069391, 2023). "In conclusion, ADAM17 is upregulated in most cancers, particularly HCC, and is critical in the development and immune evasion of HCC." (PMID 38069391, 2023). "Part of the study sample used for the GWAS of ADAM17 included participants from the Icelandic Cancer Project." (PMID 37958866, 2023). "As such, combination therapy with an ADAM17 inhibitor and cisplatin synergistically enhanced cancer cell apoptosis, and this approach holds promise for enhancing therapeutic efficacy in the future." (PMID 37175410, 2023).
cancer (continued). "There are indications that high concentrations of sPD-L1, together with high expression of ADAM10 (ADAM Metallopeptidase Domain 10) and ADAM17 (ADAM Metallopeptidase Domain 17) acted as predictors of poor response to immunotherapy in cancer patients." (PMID 37816808, 2023). "A recent study has shown that ADAM17 inhibition can impair endothelial cell necroptosis and further prevent cancer metastasis, indicating the potential of this ADAM to serve as a potential target for the treatment of advanced-stage malignancies." (PMID 37175410, 2023). "ADAM17 is a well-characterized protease involved in a plethora of physiological and pathological processes including metabolic syndrome, diabetes, and cancer." (PMID 38137406, 2023). "Previous findings with other ADAMs have shown that both ADAM10 and ADAM17 are regulated by RT and subsequently affect the cancer response to ionizing radiation." (PMID 37495855, 2023). "Aderbasib (INCB007839), which is a selective ADAM17 inhibitor currently used in clinical trials for cancer, abolished the binding of ADAM17 to E2 in a dose-dependent manner." (PMID 37766277, 2023). "It has been revealed that ADAM17 and miR-145 share the common binding domain, and ADAM17 is a direct substrate of miR-145, which contributes to the migration and invasion of cancer." (PMID 37521117, 2023). "In recognition of the importance of ADAM17 for inflammatory disease and cancer, there have been numerous attempts by Pharma to develop safe ADAM17 inhibitors." (PMID 36720499, 2023). "In cancer cells, where ADAM17 is highly expressed and active, ADAM17 directly cleaves ephrin-A1 and thereby disrupts EphA2/ephrin-A1 binding." (PMID 36998455, 2023). "ADAM17-mediated CD16 reduction has been increasingly studied for NK cell-based cancer immunotherapy as a strategy to optimize NK cell ADCC." (PMID 37669308, 2023). "These differential ADAM17-regulated levels of EphA2 pS897 directly correlated with ADAM17-dependent cancer cell migration." (PMID 36998455, 2023). "Protein–protein interaction (PPI) network analysis revealed that ADAM17 plays a core role in cancer development and immune evasion." (PMID 38069391, 2023). "Owing to the action of ADAM17−/−-educated macrophages, the invasive ability of cancer cells is reduced." (PMID 38069391, 2023). "Cancer cell migration in dependence of IR, EphA2, and paracrine signaling mediated by ADAM17 was determined using transwell migration assays." (PMID 36998455, 2023). "As ADAM17 can cleave and thereby activate cytokines and cytokine receptors, such as TNF and IL-6, most studies to date have focused on the role of ADAM17 in inflammation and cancer." (PMID 37046278, 2023). "For example, the molecular targets of ADAM10 and ADAM17 in inflammation and cancer are tumor necrosis factor-alfa (TNF alfa), inteleukin-6 (IL-6), ICAM-1 and epidermal growth factor (EGF)." (PMID 37185715, 2023). "A total of 35,559 Icelanders were recruited in the GWAS of circulating ADAM17, with 52% of them originating from the Icelandic Cancer Project and 48% from the deCODE study." (PMID 37958866, 2023). "ADAM17 expression was analysed in pan-cancer and HCC tissues using The Cancer Genome Atlas and Genotype-Tissue Expression datasets." (PMID 38069391, 2023). "TACE or ADAM17 inhibitors have been used in clinical trials for cancer treatment and are commercially available." (PMID 36288690, 2022). "ADAM17 has over 90 substrates, some of which are mediators of cancer diseases, which implies that substrate based ADAM17 inhibitors have the potential to be used for the treatment of malignant tumors." (PMID 36466812, 2022). "The α-secretase ADAM17 is strongly expressed in high-grade cancers and biopsies from patients with low survival rates, and thus is considered a marker of carcinogenesis progression and poor prognosis." (PMID 35216240, 2022).
cancer (continued). "The zebrafish in vivo invasion model revealed that injection of SW480 cancer cells with preconditioned macrophages enhanced cell dissemination into the tail region and that cancer cell–derived ADAM17 was required to obtain this effect." (PMID 35998057, 2022). "It is possible that Tspan8 regulates additional ADAM17 substrates that are involved in intra- and extravasation, which were not part of this study, leading to enhanced metastasis of Tspan8-expressing cancer cells." (PMID 36078095, 2022). "Because ADAM17 displays an important role in inflammatory diseases, it has been proposed as a therapeutic target in several kinds of cancer, including EOC." (PMID 35216240, 2022). "To test this, we isolated bone marrow–derived macrophages (BMDMs) from female WT mice and cultured them with WT or Adam17–/– cancer cells, separated by a porous membrane allowing only soluble molecules to pass." (PMID 35998057, 2022). "This study investigated ADAM17 expression in cancer patients and/or normal individuals by bioinformatics analysis." (PMID 35720350, 2022). "Depletion of ADAM17 in cancer cell lines reduced the expression of several protumorigenic markers in neighboring macrophages in vitro as well as in mouse models." (PMID 35998057, 2022). "ADAM17 expression in tumors was higher than that in several paired normal tissues and was negatively correlated with the prognosis of patients with malignant tumors." (PMID 35720350, 2022). "Together, our data indicate that HB-EGF, shed from cancer cells by ADAM17, amplifies TNF-α and CSF-1 signaling in nearby macrophages." (PMID 35998057, 2022). "ADAM17 is widely present in endothelial cells and is positively correlated with immune infiltration levels of endothelial cells in multiple cancer species." (PMID 36466812, 2022). "ADAM17 expression correlates to the expression of protumorigenic macrophage markers in multiple cancer types." (PMID 35998057, 2022). "Higher levels of ADAM17 protease were found in multiple cancer types in comparison to the cellular environment of normal tissue." (PMID 35958270, 2022). "It was found that CD, TQ, and m62A repressed the ADAM17 expression upon different cancer cells remarkably." (PMID 36558177, 2022). "We cocultured PMA-induced THP-1 macrophages with SW480 cancer cells, transfected with either NC or ADAM17 siRNA for a total of 48 hours." (PMID 35998057, 2022). "Previously, it was found that ADAM17 expression was higher in tumors than in normal tissues, and that it reduced the prognosis of patients with malignant tumors." (PMID 36558177, 2022). "Previously, we studied the expression of ADAM17 in cancer patients and/or normal subjects using bioinformatics analysis." (PMID 36558177, 2022). "In a previously published paper, we explored ADAM17 protein or its mRNA expression in pan-cancer and adjacent normal tissues." (PMID 36558177, 2022). "Although reaching statistical significance in 4T1 cells only, these experiments revealed that ADAM17 is involved in macrophage-induced cancer cell invasion and that 1 or more ADAM17-dependent soluble factors regulates this process." (PMID 35998057, 2022). "Taken together, cancer cells educate macrophages toward a protumorigenic phenotype, promoting the invasion of cancer cells via ADAM17-dependent soluble factor(s)." (PMID 35998057, 2022). "Then, the ADAM17 mRNA expression profile across distinct tumors and the corresponding normal tissues in pan-cancer were assessed with the GEPIA dataset." (PMID 35720350, 2022). "In order to extend the study of ADAM17 in the crosstalk between macrophages and cancer cell invasion to an in vivo context, we took advantage of the zebrafish embryo dissemination model." (PMID 35998057, 2022). "Due to the indispensability of the immune system during antiviral processes, the correlations between the expression of ADAM17 and the level of immune infiltration in cancers were performed." (PMID 35720350, 2022).
cancer (continued). "Studies have revealed that malignant phenotypes of several cancer types are closely relevant to highly expressed ADAM17." (PMID 36558177, 2022). "To get a deeper understanding of ADAM17-dependent macrophage education, we performed RNA-Seq of macrophages following coculture with WT versus Adam17–/– cancer cells." (PMID 35998057, 2022). "We now show, in a variety of cancer cell lines, that depletion of ADAM17 alters the macrophage phenotype in human and mouse tumors." (PMID 35998057, 2022). "Our finding is further supported by notion that ADAM17 mediates the invasive growth of the carcinoma." (PMID 36497350, 2022). "Aderbasib (INCB007839), is a selective inhibitor of ADAM10 and ADAM17, which is currently in clinical trials for cancer treatment." (PMID 33684175, 2021). "All these studies suggested that ADAM17-mediated cleavage of the IL-6R is responsible for the tumorigeneses and progression of cancer." (PMID 34182543, 2021). "The published data on the relationship between the expression of several ICs—PD-L1, B7-H3, B7-H4, IDO1, Gal-3 and -9, CEACAM1, CD155, Siglec-15, and the ADAM17 immune response modulator—with the prognosis of cancer tumors, including GC, are analyzed." (PMID 34943606, 2021). "Increased ADAM17 expression is identified in several inflammatory diseases, cancers, and organ fibrotic changes, including IPF." (PMID 34362154, 2021). "Taken together, CRC-derived exosomal ADAM17 stimulated cancer cell migration via cleavage of E-cadherin and the upregulation mesenchymal expression." (PMID 34650435, 2021). "Even though the role of ADAM17 in cancer is generally well-studied, its impact on resistance mechanisms is not completely understood; especially, the impact of 3D culture condition on ADAM17 and its effects on apoptosis has not yet been characterized." (PMID 33922533, 2021). "Our group showed that the tetraspanin CD9 negatively regulated integrin α5β1-mediated adhesion of cancer cells both to its canonical ligand fibronectin and to ADAM17 as a novel ligand." (PMID 34576100, 2021). "Excess ADAM17 activity contributes to an increased release of EGFR ligands, which can promote cancer evolution, whilst low ADAM17 activity can determine problems in development and regeneration caused by decreased EGFR signalling." (PMID 34362154, 2021). "Although the role of ADAM17 in cancer cells has been well studied, the secreted ADAM17 effects transported via exosomes are less understood." (PMID 34650435, 2021). "Notch signaling plays also a regulatory role in maintenance of cancer stem-like cells (CSC) phenotype and Notch proteolytic activation by ADAM17 was implicated in promotion of liver CSCs upon iNOS over-expression." (PMID 33805340, 2021). "This review provides an overview of the role of ADAM17 in EMT-associated pathways, highlighting new therapeutic perspectives on fibrotic diseases and cancer." (PMID 34362154, 2021). "ADAM17 showed high hazard ratios in bladder (HR 4.65; p 0.04), brain (HR 3.65; p 0.0004) and colorectal (HR 2.0; p 0.024) cancers." (PMID 33796097, 2021). "This is intriguing because ADAM10 and ADAM17 have recently been shown to cleave PD-L1 from the surface of cancer cells." (PMID 33672843, 2021). "Given its capability as sheddase, ADAM17 plays a multifunctional role in cancer progression that can vary among different cancer types and phases of the disease." (PMID 34362154, 2021). "Since its discovery, ADAM17 has been defined as the “enzyme that does it all”, playing a pivotal role in several areas of cancer and inflammation." (PMID 34362154, 2021). "Generally, high levels of ADAM17 are associated with poor cancer prognosis due to the exacerbation of EGFR signaling, but it can play additional roles in different phases of cancer progression." (PMID 33579029, 2021). "Human diseases including inflammatory, immune, degenerative diseases and cancer were confirmed to be related to ADAM17." (PMID 34182543, 2021).
cancer (continued). "The irradiation-induced signaling pathways evoked by ADAM17 as a mediator for intercellular communication and their implications for cancer growth and therapy still need to be elucidated." (PMID 36860547, 2021). "We also demonstrated that the effects of exosomal ADAM17 are mediated via E-cadherin cleavage, which promotes cancer cell dissemination from the primary lesion to distant organs by enhancing motility as well as migratory and invasive properties." (PMID 34650435, 2021). "We reviewed data on the relationship between PD-L1, B7-H3, B7-H4, IDO1, Galectin-3 and -9, CEACAM1, CD155, Siglec-15 and ADAM17 expression with cancer development in complex with the results of clinical trials on their inhibition." (PMID 34943606, 2021). "Our results in the present study show that similar regulatory mechanisms were exerted by CD9 on the adhesion-supporting capacity of ADAM17 when this tetraspanin was expressed on the surface of cancer-derived exosomes." (PMID 34576100, 2021). "Studies have described the role of ADAM17 as an important regulatory hub in development, immunity and cancers." (PMID 34281556, 2021). "Being implicated in essential signalling pathways of the immune system, organ fibrosis and cancer progression makes ADAM17 an attractive therapeutic target." (PMID 34362154, 2021). "ADAM17 has been found to be a promising therapeutic target for cancers of many tissues including breast, brain, colon, kidney, lung, liver, ovaries, pancreas and prostate." (PMID 33904577, 2021). "Two monoclonal antibodies D1 (A12) and MEDI3622 directed against ADAM17 were demonstrated to be efficient in pre-clinical cancer models." (PMID 32698506, 2020). "Accordingly, ADAM17 inhibition is beneficial across multiple models of inflammation and cancer, and therefore represents an attractive therapeutic target." (PMID 32050662, 2020). "MMP-9, MMP-14, ADAM-12 and ADAM-17 are some of the MPs that were found to have a significant role in several types of cancer." (PMID 32466129, 2020). "ADAM17, also named the tumor necrosis factor-alpha converting enzyme (TACE), is a member of the ADAM protein family, which is associated with inflammation and cancer." (PMID 32610677, 2020). "Given the variety of important substrates of ADAM10 and ADAM17 in breast cancer as well as other cancers, this study sheds new light on the potential complications associated with these common xenoestrogens." (PMID 32265938, 2020). "ADAM17 promoted cancer progression mainly by shedding Tumor Necrosis Factor-alpha (TNF-α) to activate the downstream signaling pathways." (PMID 32637415, 2020). "Our screens identify phosphorylation sites in the cancer target ADAM17 that are regulated through a conserved B56 binding site." (PMID 32400009, 2020). "We measured the enzymatic activity of ADAM17 in these cell lines, and found that ADAM17 activity as well as mRNA expression increased after gemcitabine treatment in cancer cell lines." (PMID 33273652, 2020). "Another mechanism behind the reduction in the amount of mCX3CL1 on a cancer cell is an increase in the expression of ADAM10 and TACE/ADAM17, enzymes releasing sCX3CL1, which results in a reduction in mCX3CL1 on a cancer cell." (PMID 32466280, 2020). "It is known that ADAM17 mediates the cleavage of the substrates involved in brain pathology, inflammation, and cancer." (PMID 32028607, 2020). "Recent in vitro and mouse studies have shown the involvement of ADAM17 in inflammation and cancer pathways." (PMID 33143292, 2020). "Targeting ADAM-17 with either small molecular weight inhibitors or monoclonal antibodies has been demonstrated to induce anti-cancer activity." (PMID 32948029, 2020). "The enhanced release of EGFR ligands via ADAM17 was shown to drive cancer progression and drug resistance in cell lines and experimental mouse models (see also below)." (PMID 32698506, 2020). "Taken together, ADAM17 was an essential factor in regulating drug-resistance and cell metastasis of human cancer." (PMID 33005106, 2020).